CD163 (CD163 molecule)
Diseases named in the same sentence as CD163 in open-access papers (continued):
Sharing a sentence is not in itself a finding about the gene and the disease.
tumor (continued). "Primary and metastatic colon cancer sections showed positive staining for CD163+ macrophages; TGF-β1 expression was mostly restricted to stromal and immune cells, with negligible expression in tumor cells." (PMID 35230974, 2022). "The proportion of M2-like macrophages (CD163+CD204+CD206+) was significantly increased in tumor tissues, while the proportion of M1-like macrophages (CD163−CD14−CD206+) was decreased in tumor tissues." (PMID 35725444, 2022). "To get more convincing evidence, after patients informed consent, we collected 8 PCP tumor samples for immune historical staining and 5 biomarkers of immune infiltration cells were detected including CD4, CD8, CD20, CD56, and CD163." (PMID 36389809, 2022). "CD14+ cells from tumour tissue have higher expression of the macrophage markers CD68, CD206 and CD163 but only CD163 was increased in patient blood CD14+ cells." (PMID 34727230, 2022). "We identified higher proportions of CD68+, CD68+CD163+, and CD68+CD206+ TAMs in tumor tissue than in the adjacent area (t-test, p < 0.05)." (PMID 36230558, 2022). "Higher scores for moderate/high expression of CD163 were observed in PDLIM2-positive stroma and intra-tumour infiltrates than in PDLIM2-negative tumours, while the scores for low CD163 expression were similar." (PMID 36531051, 2022). "In the tumor microenvironment, the presence of M2-like TAM, usually defined by the expression of CD163 and CD206, is generally regarded to exert immunosuppressive or proangiogenic effects." (PMID 35503656, 2022). "Those lesions exhibited significantly higher densities of tumour microenvironment cellular infiltrate including CD4, FOXP3, CD163 and PDL-1, potentially indicating a role for the inflammatory immune response in disease progression." (PMID 36224403, 2022). "With progressive expansion of the VS and thus increasing tumor volume, the expression of the macrophage markers CD68 (r = 0.28, p < 0.0001) and CD163 (r = 0.19, p = 0.02) increased weakly." (PMID 36139588, 2022). "Upon histopathological analysis, along with histopathological classification and staging, the degree of CD4, CD8, and CD163 cell infiltrations and expressions of interleukin-6 and matrix-metalloproteinase-11 (MMP-11) in the primary tumor were assessed." (PMID 36010928, 2022). "Next, the tumor-supporting M2-TAMs (CD11b+/CD163+) and control TAMs (CD11b+/CD163−) were sorted by fluorescence-activated cell sorting (FACS) using the well-known TAM labeling CD11b and the classic M2-TAM labeling CD163." (PMID 35927251, 2022). "To confirm the results obtained by comprehensive bioinformatics analysis, we performed immunohistochemical staining of tumor tissues from 80 patients with PTC and 18 patients with ATC for the M2 macrophage marker CD163 and the Treg marker Foxp3." (PMID 35222534, 2022). "Thus, based on these findings, we propose that CD163 could be regarded as a biomarker for tumor progression and clinical outcomes in CRC, where a low expression may be seen in the early stages of development, and high expression may suggest invasion, metastasis, and a low survival rate." (PMID 36551651, 2022). "In CXCL13/CD163 double staining, CXCL13 was stained red in the cytoplasm of both tumor cells and TAMs, whereas CD163 was visible in brown plasma membrane staining of M2 macrophages." (PMID 35570844, 2022). "The number of CD163+ and CD206+ cells also trended lower in Gpr35ΔMΦ compared with Gpr35fl/fl tumours." (PMID 33758004, 2022). "This is the first study to report a direct and strong correlation between densities of CD163+ or FoxP3+ cells and densities of CD8+ cells combined in the tumor center (TC) and tumor invasive margin (IM)." (PMID 36551693, 2022). "IHC performed on tumor biopsies done before C2D1, showed that percentages of PDL1+ tumor cells, ratio of CD3+ on CD163+ cells and density of FOXP3+ cells were significantly higher in patients with DCB than without DCB." (PMID 35794623, 2022).
tumor (continued). "In tumor-dominant ROIs, however, several proteins appeared to be upregulated, including MHCII, OX40L, and the macrophage marker CD163." (PMID 35418199, 2022). "The maximum intensity projection of multiplexed data was used to determine the patch type between tumor (Pan-Keratin+E-cadherin), stroma (COL1+SMA), CD8ɑ, M1 (HLA-DR+CD68), and M2 (CD68+CD163+CD206)." (PMID 36050391, 2022). "To validate our findings, we carried out IHC staining of all the primary tumour samples using a customised in house immune panel to evaluate the presence of CD3+, CD8+, CD163+, FOXP3+ and PD-L1+ cells." (PMID 36253523, 2022). "Significant suppression of CD163 and CD209 expression and suppression of mRNA expression with subsequent reduction in MMP-9, RANTES, VEGF production (tumor growth factors secreted by macrophages)." (PMID 36140188, 2022). "On these bases, we would like to propose the hypothetical scenario that the FoxP3+ and CD163+ cells which infiltrate the tumor constitute suppressor circuits, which are, in essence, derived by and are intrinsically linked to the immune system, rather than being organized by the tumor cells." (PMID 36551693, 2022). "In the primary tumor, the expression of all 12 markers (CD8, CD68, Foxp3, CD11c, CD163, CD66b, CD56, CD20, PD-L1, VEGFR-2, Ki67, IFN-γ) in the PT region was lower than that in the TF region (p < 0.05)." (PMID 36195882, 2022). "Additional markers such as HLA-DR were included to identify the anti-tumor M1-polarized phenotype or CD163 and CD206 to define the pro-tumor M2-polarized macrophages." (PMID 36050391, 2022). "By contrast, the number of tumor-infiltrating CD68+M, CD163+M2, and CD47 cells was higher, and these cells were significantly associated with decreased OS." (PMID 34439378, 2021). "Activation of endogenous T cells within ascites samples led to significant lysis of tumor cells and M2-like macrophages (CD11b+CD64+ and CD206+/CD163+)." (PMID 33820820, 2021). "The tumor samples were stained for CD68 (total macrophage marker), CD163, CD206, CD204, CHID1 (M2 markers), inducible nitric oxide synthase (iNOS), IDO1 (M1 marker), FoxP3 (Treg marker), CD3 (mature T-cells marker), CD8, and PD-L1." (PMID 33466316, 2021). "In patient #1, after exposure to anti-PD-1, nodal tissue tumor spatial analysis found CD8+ lymphocytes were almost exclusively on the periphery of the tumor zone, and macrophages at the periphery of the tumor area were a mixture of CD68+ and CD163+." (PMID 34771650, 2021). "Regarding to TAMs, it has been revealed that CD68+/CD163 + M2 TAMs progressively accumulated from the tumor nest and distant locations in the TME towards the invasive front of the tumor mass in cutaneous melanoma." (PMID 34183054, 2021). "These CD163+ or CD204+ TAMs are localized in malignant areas of the pancreas, specifically around vasculature and near the invasive regions of the tumor." (PMID 35008355, 2021). "Immunohistochemistry was used to determine the tumor immunophenotype (CD3 and CD20 antibodies) and the macrophage characterization (Iba1, CD163, iNOS and MAC387 antibodies)." (PMID 34438760, 2021). "The analysis of CD68+/iNOS-negative TAMs in CRC patients showed that the presence of intensive infiltrations of M2 macrophages, CD163+ and CD68+ TAMs, in the tumor stroma was a bad prognostic, as it correlated with shorter DFS and OS." (PMID 33557173, 2021). "We then examined the changes in M2-like TAM markers (CD163, CD206, CD209, IL-10 and Arginase 1) and M1-like TAM markers (CD80, CD86, IL-12, and TNFα) induced by CM from ILT4-downregulated tumor cells." (PMID 33537094, 2021). "Even though the number of infiltrating MΦ was low, we observed a colocalization of CD163 and LDHB in decoy tumors, suggesting the presence of LDHB protein in TAMs under conditions when tumor cells are low in miR-375." (PMID 34158867, 2021).
tumor (continued). "Further, BTK was found to be co-expressed to differing degrees with SOX2, CD163, or CD68, indicative of both tumour and immune cell expression of the kinase." (PMID 34645618, 2021). "Multiplex immunofluorescence staining (mIHC) with PD-L1, CD8, CD163, Pan-Keratin and DAPI was performed with the pretreatment tumor tissue." (PMID 35095878, 2021). "Compared with adjacent normal tissues, ITGA5, CD163, STAT6 and GATA3 levels were greater in most tumor tissues." (PMID 33711961, 2021). "Overall, macrophages were the most commonly detected cell type with 69 of 141 tumor ROIs positive for CD68 by DSP and 48 of 141 for CD163." (PMID 33658518, 2021). "Immunostaining revealed many CD163‐positive TAMs (M2 macrophages), CD15, MPO‐positive TANs, and CD3, CD25‐positive Tregs in the tumor." (PMID 33174378, 2021). "There was a significant decrease in the number of tumor cells (EpCAM+, PD-L1+) and M2 like macrophages (CD11b+CD64+CD206+ and CD11b+CD64+CD163+) with PD-L1 BiTE treatment, alongside a significant increase in activated T cells number (CD3+ and CD25+)." (PMID 33820820, 2021). "In addition, DTYMK could competitively combine with miR-378a-3p to maintain the expression of MAPKAPK2 and thus activate the phospho-HSP27/NF-κB axis, which mediated drug resistance, proliferation of tumor cells, and infiltration of CD163+ M2-type TAMs by inducing the expression of CCL5." (PMID 34795209, 2021). "In an immunohistochemical analysis of a panel of immune biomarkers within the GBM microenvironment, the CD163+ pro-tumoral macrophages appeared to be the most common cell type in both the peritumoral area (PTA) and the tumor core (TC)." (PMID 34071306, 2021). "This was accompanied by a decrease in the presence of immune suppressive M2 macrophages in the lung tissues, as revealed by the significantly lower CD163 staining in DET- and DETD-35-treated mice compared to tumor control mice." (PMID 33810045, 2021). "Findings reveal, a positive correlation between the CD4+/CD163+ and CD8+/CD68+ T cell ratio which can be attributed to cross talking between macrophage surveillance and T cell signaling in tumor microenvironment." (PMID 34326381, 2021). "Noteworthily, CD163 and MARCO expression as well as the combined expression of CD163 and MARCO in tumor tissues were also correlated with DFS and OS." (PMID 34778091, 2021). "Large samples from adenectomy post-anti-PD-1 were available for pt #1, showing a near complete spatial tumor exclusion of T CD8+ lymphocytes and macrophages CD163+." (PMID 34771650, 2021). "Significant differences in the mean preoperative tumor volume were also observed for all immune cell markers (CD3, CD8, CD68 and CD163)." (PMID 33530441, 2021). "Additional multiplex IF-IHC of CD163, CD8, PD-1 and panCK was performed on 20 tumor specimens, which were stained for Rab37, IL-6 and CD45." (PMID 34093869, 2021). "Immunohistochemistry was used to determine the tumor immunophenotype (CD3 and CD20 antibodies) and macrophage characterization (Iba1, MAC387, CD204, CD163 and iNOS antibodies)." (PMID 34438760, 2021). "At the same time, the expression patterns of ZC3H12B, T cell markers CD4 and CD8, M1 type markers CD14 and CD86, and M2 type markers CD163 and CD206 were also detected in mouse tumor tissues." (PMID 33718596, 2021). "Further macrophage subsets were identified based on their high expression of CD68, CD163, and MRC1 (encoding CD206), which could be denoted as resident tissue macrophages and segregated into normal colon epithelial tissue (NLRP3+ and phospholipid transfer protein PLTP+) or tumor tissue (IL1B+)." (PMID 34572013, 2021). "High infiltration of tumor-infiltrating CD8+, CD4+, and FOXp3+ regulatory (Tregs) T cells and low CD163+ M2 macrophages (TAMs) were found to be significantly correlated with a longer overall survival in eCCA patients." (PMID 34083572, 2021). "Increased frequencies of CD163+, CD204+ and CD206+ TAMs correlate with tumor progression and worse clinical prognosis." (PMID 34638388, 2021).
tumor (continued). "Under these conditions, treatment with H22-dPBD effectively eradicated both blood monocytes and tumor-infiltrating CD14+ cells, some of which expressed CD163, a representative TAM marker." (PMID 33692791, 2021). "Both mIgG4 or mIgG1 induced a significant reduction of CD14, CD163 and CD206 expression in M2a cells from healthy, primary tumor, and metastatic patients compared to unstimulated M2a controls." (PMID 33628623, 2021). "An increase in T cell activation was observed alongside a significant decrease in ascites tumor cells and macrophages (PD-L1+ and CD206+/CD163+ population)." (PMID 33820820, 2021). "Overall, these studies highlight that an immunosuppressive microenvironment (i.e., CD163+ M2-macrophages, dysfunction of DCs and NKs) can be observed in MPM and, thus, contributes to the escape of the tumour from immune surveillance." (PMID 34206956, 2021). "Of note, a recent study evaluating 44 cases of MBC versus 174 cases of TNBC found more CD163+ cells in the stroma and less CD8+ cells in the tumor of MBC cases." (PMID 34168978, 2021). "CD163 staining was correlated with the invasion of lymph nodes (P = 0.002), TNM stage (P = 0.017), and tumor size (P = 0.049)." (PMID 34458140, 2021). "In tumor bearing mice CCL24, CD163 and MMP7 were upregulated after therapy and IL24 and Odc1 were downregulated (p > 0.05)." (PMID 34944584, 2021). "We used IHC staining to evaluate the infiltration of tumor-infiltrating inflammatory/immune cells in the CCA microenvironment, including CD8+ T cells, FOXp3+ T cells (Tregs), and CD163+ M2 macrophages (TAMs)." (PMID 34083572, 2021). "We performed immunohistochemical analyses on post-treatment brains of each experimental group and investigated infiltrations of tumor tissues by T cells and macrophages/microglia using CD3, CD4, CD8, CD11b, CD163, C204, and PD1 and PD-L1." (PMID 34063518, 2021). "Further compartmentalization of the tumor compartment into PT Tumor (CD14 p = 0.001; CD68 p < 0.001; CD163 p < 0.001) and IT Tumor (CD14 p < 0.001; CD68 p < 0.001; CD163 p < 0.001) showed similar results." (PMID 34194435, 2021). "IHC for F4/80, CD163, and MPO was performed and a significant increase in MPO+neutrophils was found in primary tumours upon Dox+Zol treatment compared to any other treatment." (PMID 34290237, 2021). "Here, we show that strong MHCII expression in tumor cells is coincident specifically with CD68- and CD163-high subsets of NE-low tumors." (PMID 34200100, 2021). "As the CD86/CD163 ratio increases, CRC patients potentially exhibit a decreasing incidence of tumor recurrence." (PMID 34512652, 2021). "M2-like tumor-promoting macrophages are the major contributors of CSF1R signaling in the tumor microenvironment, as indicated by the significant correlation of the CSF1R gene with CD163 (M2 human macrophage marker)." (PMID 34067348, 2021). "In particular, CD68, CD163 and CD206 are extensively used to identify and quantify TAMs, in addition to their being used as prognostic markers for several tumor types." (PMID 34638388, 2021). "Heatmaps show enrichment scores (NES) of GO pathways in primary tumors and LN metastases according to NE-low and NE-high phenotype, CD68+, CD163+, CD33+ cellular densities and MHCII-expression in tumor cells (in brief: macrophage-related parameters)." (PMID 34200100, 2021). "We performed a thorough immunohistochemical analysis on post-tumor tissues from simultaneous versus sequential treatments involving CD3, CD4, CD8, CD11b, CD163, CD204, and PD1, PD-L1." (PMID 34063518, 2021). "As the CD86/CD163 ratio increases, CRC patients also potentially exhibit a decreasing incidence of tumor recurrence." (PMID 34512652, 2021). "We found CD68+, CD163+, CD206+, CD204+, and CHID1+ TAMs mainly distributed in the tumor stroma and tumor nest." (PMID 33466316, 2021). "CD163+ TAM distribution in tumor sites is closely related to EMT, possibly because their IL-1β production can enhance EMT, promoting tumor cell migration and invasion." (PMID 33995371, 2021).
tumor (continued). "We observed a significantly higher percentage of CD68+ macrophages (21–27%) in all examined tumor areas when compared to CD45+ leucocytes (ca. 3–7%); CD163+ cell infiltration was between 5 and 15%." (PMID 34654395, 2021). "The tumor tissues presenting VAP-1/CD68, VAP-1/iNOS, and VAP-1/CD163 coexpression were detected in 47 (43.52%), 29 (26.85%), and 49 (45.37%) specimens respectively." (PMID 32349342, 2020). "In addition, even though we report on two M2 macrophage groups (CD163+ or CD206+), we acknowledge that these may indicate the same cells, as M2a and M2c cells can express both markers, while tumor macrophage studies show approximately half of CD206+ macrophages expressed CD163." (PMID 33030647, 2020). "While, the CD163/CD68 + cells ratio as predictive index for a poorer prognosis of DLBCL is still controversial, M2 macrophages seems to have an active role in tumor progression in DLBCL patient." (PMID 32731512, 2020). "For example, leukemia inhibitory factor (LIF) promotes the infiltration of CD163+CD206+ M2 macrophages, and the blockade of LIF in LIF-expressing tumors increases the production of CXCL9, attracting cytotoxic CD8+ T cells to the tumor site." (PMID 32707850, 2020). "Noteworthy, CD163+ TAM infiltration was inversely and significantly correlated with NANOG expression, in both the stroma (p = 0.001) and tumor nests (p = 0.03)." (PMID 32630659, 2020). "Subsequently, we further confirmed that M2 macrophages (CD163 +) were enriched in human ICC tissues and secreted IL-10 to exert their tumor-promoting effects." (PMID 33372604, 2020). "This is hinted by the comparison of nodes with discordant treatment effects, which demonstrated an increased number of tumor-infiltrating CD8 T cells and CD163+ macrophages and decreased stromal FoxP3+ Tregs in nodes with 100% TE." (PMID 33344227, 2020). "Infiltration of the tumor microenvironment by CD68+ and CD163+ macrophages, Treg and CD4+ T cells (especially with Th2 phenotype), and high CD4/CD8 ratio is associated to the emergence of resistance to conventional therapy, and a worse prognosis." (PMID 34191173, 2020). "The analysis of the tumor inflammatory microenvironment composition in DLBCL patients revealed the significant increased number of CD163+ cells in the ABC group of patients and a positive correlation between CD163+ cells and STAT3 expression in tumor cells." (PMID 32731512, 2020). "It is important to note that we demonstrated how both CD163+ and CD3+ cells showed a similar gradient from the periphery to the tumor area, with most of them localizing in the bulk of the tumor." (PMID 32899203, 2020). "CD163 positive cells were significantly positively correlated with CD4 (p = 0.0405) and CD8 (p = 0.0032) positive cells in the tumor." (PMID 33244312, 2020). "Sections from these biopsies were analyzed for the presence of tumor-infiltrating CD8+, PD-1+, CD68+ and CD163+ cells." (PMID 33344043, 2020). "Flow cytometry analysis, performed with staining of CD11b, CD163, and CD206 antibodies, showed that non-tumor cell-derived exosomes were unable to promote M2 polarization." (PMID 32456301, 2020). "With respect to the immune profile of the mUM, we confirm our previous results that the main “reactive inflammatory” cell within these metastatic tumours is the M2 macrophage with an expression of CD68, CD163, and CD4." (PMID 33008022, 2020). "Image analysis automatically quantified CD68+, CD163+, and CD68+CD163− macrophage densities and CD3+ and CD8+ cells within the invasive margin (IM), tumor core (CT), and both IM and CT areas (IMCT) as well as TBs within the TB region of interest (TBROI)." (PMID 32435699, 2020). "An analysis of tumor stroma was done using CD68 for macrophages, iNOS for type 1 macrophages (M1), CD206 and CD163 for type 2 macrophages (M2), CD3 for T-cells, CD8 for cytotoxic T-cells and FoxP3 for Treg." (PMID 32933105, 2020).